PRL (prolactin)
Diseases named in the same sentence as PRL in open-access papers (continued):
Sharing a sentence is not in itself a finding about the gene and the disease.
mastitis (13 papers, 2009 to 2025). Inflammation of breast tissue during lactation or postpartum due to an obstructed duct or infection. "Fortunately, some researchers have found a high correlation between genetic polymorphisms associated with prolactin and mastitis resistance and current dairy breeds’ susceptibility to mastitis." (PMID 40427242, 2025). "The incidence of mastitis in animals is highest during calving, which is associated with increased PRL production." (PMID 36855359, 2023). "It is important to monitor serum prolactin levels before and after the treatment of mastitis to prevent relapse." (PMID 41254701, 2025). "Previous studies have shown that Limosilactobacillus (L. plantarum Q180 and L. plantarum K50) can inhibit mouse mastitis and increase PRL expression." (PMID 39456476, 2024). "The survey of Croatian GPs found that 11% (12/110) recommended infant formula during mastitis and 5% (7/155) prescribed a prolactin suppressant." (PMID 38730361, 2024). "Prolactin was thought to modulate the inflammatory response and play a role in mastitis pathogenesis." (PMID 35289670, 2022). "Methylation of the STAT5A DNA-binding sequence in the αS1-casein promoter was reported to repress the prolactin induced expression of the αS1-casein during acute mastitis." (PMID 28077797, 2017). "The study of the effect of PRL on bovine mastitis resistance is a very interesting topic." (PMID 40427242, 2025). "This study aimed to determine the nature of the distribution of the relative frequencies of alleles and genotypes of polymorphic prolactin (PRL) and nitric oxide synthase (NOS2) in Holstein cows and identify the relationship of these genes with resistance to mastitis and bovine leukemia." (PMID 36855359, 2023). "Consistent with the lactation insufficiency observed in mastitis, we found that IFN-γ and TNF-α inhibit prolactin-induced STAT5 tyrosine phosphorylation and β-casein expression." (PMID 40564173, 2025). "Many aspects of this pathway have been demonstrated in mice such as the regulation of lactation by prolactin via STAT5 and the SOCS proteins, the induction of STAT1 in conditions of sterile mastitis and the ability of STAT1 to regulate prolactin signaling." (PMID 29117179, 2017). "Though increased prolactin levels may not impair lactation, there is the rare possibility of overproduction leading to mastitis, and AP-induced mastitis has been described even in nonpregnant and nonlactating women." (PMID 39091697, 2024).
melanoma (13 papers, 2015 to 2026). A malignant, usually aggressive tumor composed of atypical, neoplastic melanocytes. "In that study, an adenoviral vector encoding the vasoinhibin isoform of 16 kDa (16k PRL) delivered 2 days post-melanoma cell intravascular inoculation, reduced the number and size of lung metastases." (PMID 40435350, 2025). "The most important canonical pathways associated with TE-predominant transcripts were prolactin signaling, melanoma, NOTCH, and HGF -signaling, and protein citrullination." (PMID 26681441, 2015). "Several studies report elevated levels of RNA and GHR proteins in human melanoma biopsies, while the cell cycle of melanoma cells has been shown to be subject to orchestrated regulation of endogenous GH, prolactin (PRL) and adrenocorticotropic hormone (ACTH)." (PMID 35160191, 2022). "This phenomenon has been well documented in human patients with melanoma, and PRL of the sentinel LN is recommended for selected patients." (PMID 34649575, 2021). "Along with several reports of elevated GHR RNA and proteins in human melanoma biopsies, the melanoma cell cycle was also considered to be under an orchestrated regulation of endogenous GH, prolactin (PRL) and adrenocorticotropic hormone (ACTH)." (PMID 28223541, 2017). "In view of these facts and our identification of a profound GH mediated regulation of melanoma progression, we wanted to look at presence of endogenous RNA levels of GH as well as PRL and PRLR in human melanoma." (PMID 28223541, 2017). "Since prolactin is also secreted by the anterior pituitary hormone and serves autocrine functions and prolactin receptor is expressed in melanoma cells, we also examined the effect of prolactin on melanoma growth in vivo." (PMID 27825319, 2016). "The treatment of melanoma with BE was associated with MicroRNAs in cancer, chemical carcinogenesis-receptor activation, Kaposi sarcoma-associated herpesvirus infection PI3K-AKT signaling pathway, and prolactin signaling pathway." (PMID 41596235, 2026). "Activin-A has been shown to be particularly important in melanoma, where it can affect metastatic potential through evasion of the immune system, and one study has shown that prolactin may be a possible early predictive factor in lung cancer patients with metastases." (PMID 37370722, 2023). "Like our studies, PRLR-inhibited/down regulated models can provide a mechanistic detail of PRL action and a putative salvage pathway involving GH-PRLR interaction specifically in melanoma." (PMID 28223541, 2017). "Although we observed a mild increase in either PRL or PRLR in the human melanoma cell lines due to doxorubicin, we did not observe any upregulation of MITF or MITF targets due to PRL addition." (PMID 31547367, 2019).
Hyponatremia (12 papers, 2014 to 2026). An abnormally decreased sodium concentration in the blood. "So GH, PRL and estrogen deficiency may be the other potential causes of hyponatremia in patients with SS who have severe PRL and GH deficiency." (PMID 39863703, 2025). "The model, incorporating preoperative prolactin, preoperative elevation of the diaphragma sellae, and early postoperative hyponatremia, demonstrated excellent discriminative ability upon internal and external validation." (PMID 41426297, 2025). "A 29-year-old woman presenting with euvolemic, hypotonic hyponatremia, normal thyroid, and glucocorticoid axes, and inappropriately concentrated urine was found to have a sellar mass with an elevated prolactin level." (PMID 37700952, 2023). "Comparing the adenohypophyseal hormones of the two groups, we found that the pre- and postoperative PRL levels in the delayed hyponatremia group were significantly lower than those in the normonatremia group (P = 0.013 and 0.033, respectively)." (PMID 36176407, 2022). "We found that the postoperative PRL level in the hyponatremia group (5.23 ng/mL) was lower than that in the normonatremia group (6.94 ng/mL), but its average value fell within the normal reference value range." (PMID 36176407, 2022). "Rinsing the isolated porcine kidneys with Biolasol + Zn + PRL had the greatest impact on the development of hyponatremia." (PMID 34200394, 2021). "She had hyponatraemia, elevated creatine phosphokinase, low thyroxine, prolactin, FSH, LH, and IGF-1." (PMID 33343948, 2020). "Hyponatremia occurred in 50% of the patients in both groups, with nadir serum sodium levels in the CD group (113–134 mmol/L) similar to those in the CD + PRL group (109–130 mmol/L)." (PMID 25506361, 2014).
lung cancer (12 papers, 2015 to 2025). A malignant neoplasm involving the lung. "Less frequently discussed hormones such as activins, follicular-stimulating hormone (FSH), and prolactin have all been implicated in other cancer types; however, little work has been carried out as regards lung cancer." (PMID 37370722, 2023). "It was shown that protein expression levels of chemokine CXCL16 which regulates inflammation, growth hormone receptor (GHR) and PRL were elevated in lung tumor tissue, which was associated with decreased survival of patients with lung cancer." (PMID 34487971, 2021). "In this study, we measured the levels of CEA, CYFRA21, and PRL in a cohort of NSCLCs and healthy controls to investigate the diagnostic efficiency of these markers and to create statistical models to advance in lung cancer diagnosis." (PMID 30555348, 2018). "In this review, we summarized the roles of sex-specific bioactive molecules (estrogens, progesterone, testosterone, FSH, LH, prolactin, leptin, activin, and inhibin) in the immune response to lung cancer and immunotherapy effectiveness." (PMID 41463203, 2025). "FSH, LH, and prolactin can all downregulate the anti-apoptotic factor HO-1 in lung cancer cells, possibly resulting in reduced tumor growth." (PMID 41463203, 2025). "Prolactin in lung cancer takes on a different role from other hormones, as lung cancers can ectopically secrete prolactin, increase general levels, and correlate with more aggressive cancers." (PMID 41463203, 2025). "PRL was introduced in a seven-analyte panel of lung cancer biomarkers for the first time and the panel was suggested useful to risk stratify cancer patients for early recurrence after resection of node-negative NSCLC less than 4 cm." (PMID 30555348, 2018). "However, like FSH and LH, stimulation of human lung cancer cells with prolactin led to downregulation of HO-1 expression and increased the ability of the lung cancer cells to infiltrate other sites in the body." (PMID 41463203, 2025). "Only a few studies have examined the relationship between the PRL levels and lung cancer." (PMID 30555348, 2018). "Among the most interesting studies conducted in the last 10 years, CancerSEEK reported a panel of eight proteins (CA-125, CEA, HGF, Myeloperoxidase, OPN, Prolactin, and TIMP-1) effective in distinguishing lung cancer patients from healthy controls." (PMID 38068296, 2023). "A study suggested that a panel of four biomarkers composed of prolactin, CRP, NY-ESO-1, and HGF to screen for lung cancer." (PMID 31976313, 2020).
somatotropinomas (12 papers, 2014 to 2025). "The incidence of combined GH + PRL was relatively low (seven cases, 4.9%), whereas somatotroph tumors with the simultaneous production of GH and PRL are common." (PMID 40002269, 2025). "Six cases with a combination of acromegaly and prolactinoma were evident, and the possibility of double PitNETs with somatotroph and lactotroph tumors should be considered, although somatotroph tumors producing GH and PRL simultaneously are common." (PMID 40002269, 2025). "Secondly, in contrast to the WHO 2017, the WHO 2022 states that somatotroph tumors are negative for PRL, raising the question how to classify bona fide somatotroph tumors with little, yet obvious intratumoral PRL expression." (PMID 38228887, 2024). "As many as 75% of CNCs present with elevated GH/IGF-I and PRL levels, and 10–12% of these cases including somatotroph tumors are slightly more common in females, developing one to two decades earlier than sporadic cases." (PMID 36010855, 2022). "Pathologically, these somatotroph tumors can be described as either adenoma or hyperplasia, with both commonly presenting as multiple foci with a mixture of GH- and PRL-producing cells." (PMID 36010855, 2022). "Twelve of the top 15 genes across all PitNETs were mitochondrially encoded enzymes and the three other genes encoded for two of the pituitary hormones GH and PRL, and the G protein GNAS, mutated in up to 50% of sporadic somatotroph tumors." (PMID 34758873, 2021). "High prolactin levels can be seen in patients with somatotroph tumors that interrupt the pituitary stalk, but the levels are higher in patients with bihormonal tumors (>200 μg/L)." (PMID 31766255, 2019). "Previous clinical studies revealed that cabergoline and bromocriptine can normalize serum PRL levels in more than 80% of prolactinomas patients and have a good effect in somatotropinoma patients, which consistent with our data from immunostaining analysis." (PMID 25027022, 2014). "Thus, based on this study, dopastatins were developed (BIM-23A387 and BIM-23A760), showing a reduced GH and PRL secretion in the primary cultures of somatotropinomas, especially in the tumors with a partial response to octreotide and lanreotide." (PMID 37109772, 2023). "Moreover, a previous study showed that addition of IGF1 (100nM) to primary cultures of somatotropinomas indeed leads to a significant decrease of GH secretion in 5/8 tumors, while increasing the PRL secretion of prolactinomas." (PMID 27267119, 2016). "An important difference lies in our rigorous inclusion criteria: not including studies involving mixed GH/PRL-secreting PitNETs or other hormonal syndromes to focus exclusively on GH-secreting somatotropinomas." (PMID 40941625, 2025).
Alzheimer disease (11 papers, 2021 to 2025). A progressive, neurodegenerative disease characterized by loss of function and death of nerve cells in several areas of the brain leading to loss of cognitive function such as memory and language. "Streptozotocin-induced Alzheimer’s disease models are known to increase brain oxidative stress, reinforcing the relevance of PRL’s antioxidant properties in this context." (PMID 39499702, 2024). "These common targets are enriched in Alzheimer's disease, serotonergic synapses, HIF-1 signal pathways, estrogen signaling pathways, alcoholism, cocaine addiction, dopaminergic synapses, prolactin signal pathways, gap junctions, and neuroactive ligand-receptor interactions." (PMID 34977242, 2021).
anovulation (11 papers, 2010 to 2025). The absence of ovulation. "Common manifestations of Hyper-PRL are anovulation, oligomenorrhea, amenorrhea, and galactorrhea." (PMID 35098010, 2021). "PCOS and Hyper-PRL have been reported to be the most common etiologies of anovulation in females." (PMID 35098010, 2021).
bipolar disorder (11 papers, 2008 to 2025). A disorder of the brain that causes unusual shifts in mood, energy, activity levels and the ability to carry out day-to-day tasks. "Up to 2 years of treatment with lurasidone in youth presenting with bipolar depression was generally safe and well tolerated, with a relatively low rate of study discontinuation, minimal impact on weight, metabolic parameters, and prolactin, and long-term improvement in depressive symptoms." (PMID 34324397, 2021). "A 2-year double-blind placebo-controlled study found that, for youth with bipolar depression, lurasidone was generally well tolerated, safe, and effective with relatively low rates of discontinuation due to adverse events, and had minimal effects on weight, metabolic parameters, or prolactin." (PMID 36422533, 2022).
Cushing syndrome (11 papers, 2008 to 2025). Cushing's syndrome (CS) encompasses a group of hormonal disorders caused by prolonged and high exposure levels to glucocorticoids that can be of either endogenous (adrenal cortex production) or exogenous (iatrogenic) origin. "This study enhances the diagnostic accuracy of inferior petrosal sinus sampling (IPSS) for differentiating pituitary from ectopic ACTH‐dependent Cushing syndrome by incorporating prolactin measurements and exploring various calculation methods." (PMID 40765079, 2025). "In comparison with the DSS group, fruit pomace intake markedly downregulated the steroid hormone biosynthesis, prolactin signaling, Cushing’s syndrome, and linoleic acid metabolism pathways, while the bile secretion pathway was upregulated." (PMID 39765807, 2024). "Compared to the DSS group, pomace intake significantly downregulated the steroid hormone biosynthesis, prolactin signaling, Cushing’s syndrome, and linoleic acid metabolism pathways, and it upregulated the bile secretion pathway." (PMID 39765807, 2024). "All of the diagnostic systems assume the exclusion of other disorders, which can be manifested by irregular menstrual cycles and/or androgen excess, such as Cushing’s syndrome, androgen-secreting tumors, increased prolactin (PRL), or luteinizing hormone (LH)." (PMID 31752081, 2019). "Likewise, cushing syndrome (bta04934), cortisol synthesis and secretion (bta04927), prolactin signaling pathway (bta04917), and ovarian steroidogenesis (bta04913) were the significantly enriched KEGG pathways for the rural_vs_mixed negative selection." (PMID 38003026, 2023).
empty sella syndrome (11 papers, 2009 to 2025). Empty sella syndrome (ESS) is a condition that involves the sella turcica, a bony structure at the base of the brain that protects the pituitary gland. "In another study, remyelination after anterior visual pathway compression injury in a patient with empty sella syndrome was shown to be sensitive to changes in serum prolactin levels." (PMID 39361237, 2025). "In summary, we demonstrate in a single patient with empty sella syndrome secondary to dopamine agonist therapy, that increasing serum levels of prolactin correlate with improved visual function and an increase in myelination of the optic tracts." (PMID 34307410, 2021). "A brain MRI was requested secondary to the elevated prolactin level which was compatible with empty sella syndrome with bowl-like widening of the sella, decreased gland height and spread inside the sella." (PMID 20184675, 2009). "A brain MRI was requested secondary to the elevated prolactin level which was compatible with empty sella syndrome." (PMID 20184675, 2009). "We have previously shown that remyelination is possible after compressive injuries to the anterior visual pathway and that measures of diffusion known to correlate with myelination are sensitive to varying levels of serum prolactin in a patient with empty-sella syndrome." (PMID 35921360, 2022). "Here we investigate mechanistic hypotheses of the effect of prolactin on glial-neuronal function in an observational study of a rare patient with symptomatic empty sella syndrome." (PMID 34307410, 2021).